GRIK2 (glutamate ionotropic receptor kainate type subunit 2)
Description:
Ionotropic glutamate receptor that functions as a cation-permeable ligand-gated ion channel, gated by L-glutamate and the glutamatergic agonist kainic acid. L-glutamate acts as an excitatory neurotransmitter at many synapses in the central nervous system (By similarity). Binding of the excitatory neurotransmitter L-glutamate induces a conformational change leading to the opening of the cation channel, converting the chemical signal to an electrical impulse (By similarity). The receptor then desensitizes rapidly and enters a transient inactive state, characterized by the presence of bound agonist. Modulates cell surface expression of NETO2 (By similarity). In association with GRIK3, involved in presynaptic facilitation of glutamate release at hippocampal mossy fiber synapses (By similarity). Independent of its ionotropic glutamate receptor activity, acts as a thermoreceptor conferring sensitivity to cold temperatures. Functions in dorsal root ganglion neurons (By similarity).
Synonyms: GluK2; EAA4; GluR-6; GluR6; MRT6; GLUK6; GLR6; NEDLAS
Tractability: Small molecule: an approved drug acts on it; a structure with a bound ligand is known; a high-quality ligand is known; it belongs to a druggable protein family. Antibody: UniProt places it where antibodies can reach, with high confidence; its Gene Ontology location is reachable by antibodies, with high confidence; UniProt predicts a signal peptide or a membrane-spanning region. PROTAC: UniProt records ubiquitination sites on it; ubiquitination databases record sites on it; its protein half-life has been measured; a small molecule that binds it is known.
Target class: Ionotropic glutamate receptor; Kainate receptor; Ligand-gated ion channel; Ion channel
Gene: Protein-coding gene on chromosome 6 (100,962,701 to 102,081,622, forward strand). Ensembl gene ENSG00000164418.
Subcellular location: Cell membrane; Postsynaptic cell membrane
Pathways (Reactome):
Neuronal System: Activation of Ca-permeable Kainate Receptor; Activation of Na-permeable kainate receptors
Gene Ontology:
Molecular function: extracellularly glutamate-gated ion channel activity; glutamate-gated receptor activity; kainate selective glutamate receptor activity; protein binding; transmitter-gated monoatomic ion channel activity involved in regulation of postsynaptic membrane potential; glutamate receptor activity; glutamate-gated calcium ion channel activity; identical protein binding; ligand-gated monoatomic ion channel activity; ligand-gated monoatomic ion channel activity involved in regulation of presynaptic membrane potential; monoatomic ion channel activity; PDZ domain binding; scaffold protein binding; signaling receptor activity; SNARE binding; ubiquitin conjugating enzyme binding; ubiquitin protein ligase binding
Biological process: glutamate receptor signaling pathway; modulation of chemical synaptic transmission; positive regulation of synaptic transmission; regulation of short-term neuronal synaptic plasticity; chemical synaptic transmission; detection of cold stimulus involved in thermoception; synaptic transmission, glutamatergic; calcium-mediated signaling; excitatory postsynaptic potential; ionotropic glutamate receptor signaling pathway; modulation of excitatory postsynaptic potential; monoatomic ion transmembrane transport; monoatomic ion transport; negative regulation of synaptic transmission, glutamatergic; neuron apoptotic process; positive regulation of neuron apoptotic process; receptor clustering; regulation of JNK cascade; regulation of postsynaptic membrane potential; regulation of presynaptic membrane potential
Cellular component: kainate selective glutamate receptor complex; plasma membrane; glutamatergic synapse; postsynaptic density membrane; presynaptic membrane; axon; dendrite; dendrite cytoplasm; hippocampal mossy fiber to CA3 synapse; ionotropic glutamate receptor complex; membrane; mossy fiber rosette; neuronal cell body; perikaryon; postsynaptic density; postsynaptic membrane; synapse; terminal bouton
Genetic constraint (gnomAD): Loss-of-function variants: 6 observed, 24.81 expected, observed/expected ratio (o/e) 0.24, 90% interval 0.13 to 0.48. The upper end of that interval is the gene's LOEUF score, 0.48, which puts it in group 2 of 6, group 1 being the genes least tolerant of losing a copy. Missense variants: 272 observed, 388.38 expected, observed/expected ratio (o/e) 0.7, 90% interval 0.63 to 0.77. Synonymous variants: 133 observed, 141.76 expected, observed/expected ratio (o/e) 0.94, 90% interval 0.81 to 1.08.
Gene-disease validity (ClinGen):
ClinGen rates the evidence that GRIK2 causes each of these diseases.
complex neurodevelopmental disorder (autosomal dominant): Definitive. A disorder that involves more than one phenotype associated with the central nervous system, including but not limited to intellectual disability, autism, and seizures (epilepsy).
complex neurodevelopmental disorder (autosomal recessive): Moderate.
Homologues: Orthologues: chimpanzee GRIK2 (100% identical), macaque GRIK2 (100% identical), rabbit GRIK2 (99% identical), dog GRIK2 (99% identical), pig GRIK2 (99% identical), guinea pig GRIK2 (99% identical), rat Grik2 (99% identical), mouse Grik2 (99% identical), tropical clawed frog grik2 (94% identical), zebrafish GRIK2 (91% identical), Drosophila melanogaster CG11155 (43% identical), Drosophila melanogaster Ekar (39% identical), and 37 more. Paralogues in human: GRIK3 (79% identical), GRIK1 (78% identical), GRIK5 (44% identical), GRIK4 (43% identical), GRIA1 (38% identical), GRIA3 (38% identical), GRIA2 (38% identical), GRIA4 (37% identical), GRID1 (28% identical), GRID2 (28% identical), GRIN1 (26% identical), GRIN2A (22% identical), and 5 more.
Diseases named in the same sentence as GRIK2 in open-access papers:
GRIK2 is named in the same sentence as 86 diseases in open-access papers, as found by Europe PMC text mining. Sharing a sentence is not in itself a finding about the gene and the disease. The quoted sentences say what the papers report.
autism (17 papers, 2011 to 2025). Persistent deficits in social interaction and communication and interaction as well as a markedly restricted repertoire of activity and interest as well as repetitive patterns of behavior. "GRIK2 has also been linked to schizophrenia and autism, while NPAS2 is associated with circadian rhythm control." (PMID 40564862, 2025). "Patient AUT35 carried a duplication in the GRIK2 gene region at 6q16.3, which has also been described as associated with autism (DECIPHER#284729)." (PMID 37107578, 2023). "Previous studies showed that the GRIK2 gene was associated with somatic anxiety, recurrent epileptic seizures, autism, and cognitive abilities." (PMID 37303955, 2023). "GRIK2 is localized in the autism-specific region on chromosome 6q21, and its encoded protein GluR6 is involved with ASD symptoms such as anxiety, learning, and memory." (PMID 36014340, 2022). "Three polymorphisms of interest were highlighted: two SNPs in GRIK2, a gene implicated in a number of neurological maladies such as autism and schizophrenia and an SNP within the NPAS2 gene, which is a putative circadian clock gene." (PMID 26859813, 2016). "One study identified chromosome 6q21 as a candidate region for autism and found a functional SNP in glutamate receptor 6 (GluR6 or GRIK2) gene associated with ASDs." (PMID 25309321, 2014). "The refined critical region contains only five genes including the obesity-associated SIM1 and the autism-associated GRIK2." (PMID 22102821, 2011). "Similarly, GRIK2 is an ionotropic glutamate receptor associated with autism." (PMID 25477900, 2014). "Several likely gene-disruptive (LGD) variants in genes such as GRIK2 and ASMT affecting autism-risk were found exclusively or more frequently in individuals with autism compared to control groups." (PMID 40373085, 2025). "The GRIK gene family (GRIK1, GRIK2, GRIK3, GRIK4, and GRIK5) has genetic variants associated with many psychiatric illnesses including; depression, obsessive–compulsive disorder, and autism." (PMID 41327126, 2025). "The GRIK gene family (GRIK1, GRIK2, GRIK3, GRIK4, and GRIK5) has genetic variants that contribute to various illnesses, including Huntington's disease, Parkinson's disease, autism, and schizophrenia." (PMID 41327126, 2025). "Several likely gene-disruptive (LGD) variants in genes such as GRIK2 and ASMT affecting autism risk were found exclusively or more frequently in individuals with autism than in control groups." (PMID 37790478, 2023). "In particular, chromosome 6q21 has been identified as an important region for autism, and a SNP was found in the glutamate receptor 6 (GluR6 or GRIK2) gene related to ASD." (PMID 28331639, 2017). "Similarly, for another of these frequent SVs, we predicted and then confirmed abnormal splicing of the glutamate receptor subunit GRIK2 in a subset of individuals with autism." (PMID 40612695, 2025). "Our analysis supports the role of several genes/loci associated with autism (e.g., NRXN1, ADNP, 22q11 deletion) and identified new truncating (e.g., GRIK2, ROBO1, NINL, and IMMP2L) or recessive deleterious variants (e.g., KIRREL3 and CNTNAP2) affecting autism-associated genes." (PMID 30675382, 2019). "Except for ARC, GRIK2 and GRID2, belonging to inotropic glutamatergic receptors, were shown to participate in neurodegeneration and psychiatric diseases, such as autism, Huntington disease and major depression." (PMID 33969375, 2021). "We confirmed several loci responsible for Autism and Pervasive Developmental Disease including MACROD2, ITGB3, CADM2, and GRIK2." (PMID 25477900, 2014). "In our previous study, we predicted aberrant splicing of the GRIK2 gene due the presence of an ASD-SV SNP near a known binding site for SRSF9, and subsequently confirmed the prediction using RNA-seq data from post-mortem brain tissue from individuals with autism." (PMID 40612695, 2025).
schizophrenia (16 papers, 2010 to 2025). A major psychotic disorder characterized by abnormalities in the perception or expression of reality. "Another study found that the rs6922753 and rs2227283 polymorphisms of the GRIK2 gene in schizophrenia were significantly related to aggressive behavior in the Chinese Han population." (PMID 31631587, 2019). "Another study reported that the rs2227283 polymorphism of the GRIK2 gene in schizophrenia was significantly related to aggressive behavior, and the A allele was a risk factor for aggressive behavior in the Chinese Han population." (PMID 31631587, 2019). "After resequencing 516 unrelated patients with schizophrenia, 44 protein-altering variants were identified, including 12 in the GRIK1, 5 in the GRIK2, 7 in the GRIK3, 13 in the GRIK4, and 7 in the GRIK5." (PMID 35629206, 2022). "Therefore, we sequenced the exonic regions of five kainate receptor genes (GRIK1, GRIK2, GRIK3, GRIK4, and GRIK5) to identify rare pathogenic variants in patients with schizophrenia using the ion semiconductor sequencing method." (PMID 35629206, 2022). "A splice variant within GRIK2 6:102337505, c.1525–10 C > T (p = 4.43 × 10−8; OR = 42.26, CI 2.53–704) and a missense variant within GRIK3, R865G, (p = 6.8 × 10−6; OR = 73, CI 4–1226) showed a significant nominal association with risk for schizophrenia." (PMID 31844109, 2019). "Among them, GRIK2 has been reported to have positive association with schizophrenia while others have not." (PMID 20613869, 2010). "In a cohort of 250 patients with chronic schizophrenia under clozapine treatment, the impact of SNPs in SLC1A1, Glutamate Ionotropic Receptor Kainate Type Subunit 2 (GRIK2), and N-methyl-D-aspartate receptor subunit 2B (GRIN2B) genes on OCS was assessed." (PMID 37627285, 2023).
epilepsy (14 papers, 2009 to 2025). A brain disorder characterized by episodes of abnormally increased neuronal discharge resulting in transient episodes of sensory or motor neurological dysfunction, or psychic dysfunction. "One of the methods proposed for epilepsy treatment is to block the expression of GluK2, a kainate receptor subunit encoded by the Grik2 gene." (PMID 39937026, 2025). "Epilepsies have been linked to KARs, including GluK2, and Grik2 knockout mice have reduced susceptibility to seizures induced by kainate, a high-affinity KAR agonist." (PMID 36899667, 2023). "Among the genes studied here, App and Grik2 are specifically relevant to study in this region, as they are respectively associated with Alzheimer’s disease and epilepsy, two pathologies that affect the hippocampus." (PMID 34504093, 2021). "Similarly, pathogenic mutations in GRIK2 are associated with intellectual disability, dysmyelination, and epilepsy, underscoring its role in excitatory neurotransmission and early motor function development." (PMID 40870030, 2025). "In addition, polymorphisms of GRIK2 were associated with an increased risk of epilepsy in children, while polymorphisms of CARS2 were associated with severe progressive myoclonic epilepsy and mitochondria-related diseases." (PMID 40843195, 2025). "In an animal model of epilepsy, the kainate receptor, specifically glutamate ionotropic receptor kainate type subunit 2 (GluK2), undergoes S-nitrosylation, and SNO-GluK2 further potentiates calcium influx." (PMID 37764469, 2023). "The kainate receptor, specifically, the glutamate ionotropic receptor kainate type subunit 2 (GluK2), undergoes S-nitrosylation in an animal model of epilepsy." (PMID 34575960, 2021). "In humans, a downregulation of GRIK2 has already been shown in patients with epilepsy." (PMID 36899667, 2023). "Using qRT–PCR, we validated the downregulation of ASD-related genes involved in cerebellar development (Cadps2 and Reln) (refs 28, 43), and ASD- or epilepsy-related ion channels in neurons (Cacna2d1, Grik2 and Kcnd2) (refs 43, 44, 45) in ICRF-193 treated or Chd7 mutant CGNs." (PMID 28317875, 2017). "Similar to the interpretation of a previous study in epilepsy, a compensatory mechanism against neuronal hyper-excitability in the frontal cortex of ALS-Ox cases could be suggested for the increased Q621R GRIK2 recoding." (PMID 38997636, 2024). "Additionally, the mediumblue module (Pvalb subtypes, 173 genes), while not passing the test for associating more strongly with epilepsy than with any sample, included the genes GRIK1, GRIK2, GRIK4, GRM1, GRM7, and GRIA1, suggesting a potential involvement in glutamate receptor subunits." (PMID 33028830, 2020).
depression (10 papers, 2009 to 2025). "The gene codes the Glutamate Ionotropic Receptor Kainate Type Subunit 2, suggesting that glutamatergic transmission may be one factor with differential associations between susceptibility to depression and severity (as reflected by duration) of illness." (PMID 34389699, 2021). "The expression levels of GRIK1 and GRIK2 were reported to be higher in the female patients with major depressive disorder." (PMID 37065490, 2023). "The aberrant expression of GRIK2 has been reported to be involved in regions, functional genes, biological function, and pathways that mediate depression disorder." (PMID 36159969, 2022).
Intellectual disability (9 papers, 2009 to 2025). "GRIK2 is associated with dominant neurodevelopmental delay, impaired language, and ataxia (MIM: 619580) and with recessive intellectual disability (MIM: 611092)." (PMID 38685113, 2024). "Altered RNA editing levels of both the glutamate receptor GRIK2 and the tryptophan hydroxylase TPH2 were also found in the brain of patients with psychiatric disorders and intellectual disability has been reported in patients with ADAR1 mutations." (PMID 24637888, 2014).
gastric cancer (7 papers, 2012 to 2023). A primary or metastatic malignant neoplasm involving the stomach. "Former study showed that the hypermethylation silencing of GRIK2 results in decreased colony formation and invasion, in gastric cancer cells." (PMID 37483484, 2023). "Glutamate receptor ionotropic kainate 2 (GRIK2) is a protein that plays a tumor suppressor role in gastric cancer." (PMID 28512631, 2017). "GRIK2 was expressed in normal gastric tissue; however, its expression was repressed in gastric cancer tissues by GRIK2 promoter region methylation." (PMID 28418868, 2017). "GRIK2 was reported to be a potential tumor suppressor gene in gastric cancer." (PMID 28418868, 2017). "Furthermore, overexpression of GRIK2 in gastric cancer cells decreased colony formation and cell migration." (PMID 28418868, 2017). "Previous studies have shown that GRIK2 may play a tumor-suppressor role in gastric cancer." (PMID 36168622, 2022). "GRIK2 is expressed in some normal organs including stomach, and a recent study revealed that GRIK2 transcription was repressed by hypermethylation of promoter region in gastric cancers, suggesting that GRIK2 might be a novel tumor suppressor gene in gastric cancers." (PMID 28418868, 2017). "GRIK2 is often highly methylated in cell lines and gastric cancer primary tumors, but not in normal adjacent tissues, leading to gene silencing." (PMID 28512631, 2017).
breast carcinoma (6 papers, 2012 to 2022). "The study also identified 22 unique ion channels in the metastatic state, of which GRIK2, GJB3, KCNB2, KCNA1 and KCNK2 were previously reported in breast cancer metastasis." (PMID 35326596, 2022).
Anxiety (5 papers, 2020 to 2024). Intense feelings of nervousness, tension, or panic often arise in response to interpersonal stresses. "Curiously, in young adult rats with anxiety-like behaviors, the genes Grin1 and Grik2, which code for subunits of different glutamate receptors, were differentially regulated compared with controls of the same age." (PMID 35998298, 2023). "The GRIK2 knockout mice showed decreased fear and memory, anxiety, and despair." (PMID 36699455, 2022). "GRIK2 and GRIA1 have been confirmed as molecular basis of neurodegeneration and domestication-related behavioral alterations like fearfulness, anxiety, social exploration, learning and memory." (PMID 32131728, 2020).
autism spectrum disorder (4 papers, 2014 to 2022). A spectrum of developmental disorders that includes autism, and Asperger syndrome. "Previously, polymorphisms in GRIK2 gene have been reported to exhibit associations with obsessive-compulsive disorder and autism spectrum disorders." (PMID 27605030, 2014). "GRIK2 encodes for a glutamate receptor that has been associated with autistic-spectrum-disorders and neuropsychiatric diseases." (PMID 25016475, 2014). "In addition, several studies found that the GRIK2 gene may be associated with autism spectrum disorder." (PMID 35629206, 2022).
obsessive-compulsive disorder (4 papers, 2014 to 2017). A disorder characterized by the presence of persistent and recurrent irrational thoughts (obsessions), resulting in marked anxiety and repetitive excessive behaviors (compulsions) as a way to try to decrease that anxiety. "DLGAP1 interacts with the glutamate receptor GRIK2, also implicated in obsessive-compulsive disorders." (PMID 29045412, 2017). "Obsessive-compulsive disorder (OCD) is genetically linked to abnormalities in the GluK2 gene, Grik2." (PMID 25750618, 2015). "Obsessive-compulsive disorder is also genetically linked to abnormalities in Grik2, the gene coding for GluK2." (PMID 24707399, 2014).
bipolar disorder (3 papers, 2014 to 2024). A disorder of the brain that causes unusual shifts in mood, energy, activity levels and the ability to carry out day-to-day tasks. "This study showed that the rs2227283 polymorphism of the GRIK2 gene in people from the Han population may be associated with the occurrence of aggression in bipolar disorder, and the A allele was a risk factor in aggressive behavior." (PMID 31631587, 2019). "In this study, we examined the relationship between the GRIK2 gene and aggressive behavior in patients with bipolar disorder." (PMID 31631587, 2019). "While several studies showed no alteration in schizophrenia and bipolar disorder, a recent study revealed altered editing of the I/V site of GRIK2 in bipolar disorder." (PMID 24443933, 2014).